FZD7 (frizzled class receptor 7)
Diseases named in the same sentence as FZD7 in open-access papers (continued):
Sharing a sentence is not in itself a finding about the gene and the disease.
tumor (continued). "Fzd7, a receptor for Wnt ligands, is upregulated in various malignancies, including PCa, where it plays a pivotal role in tumour progression." (PMID 41007281, 2025). "Using humanized Fzd7 mice, we show that a highly specific FZD7 antibody enables isolation of FZD7+ tumor cells with enhanced growth potential and selective sensitivity to a FZD7-antibody drug conjugate (ADC)." (PMID 41218118, 2025). "FZD7 is the most well-studied paralog in cancer and its overexpression has been documented across numerous tumor types." (PMID 40376615, 2025). "Future studies dissecting downstream signaling events in Fzd7-positive basal cells will be essential for clarifying how FZD7 sustains tumor growth and for identifying additional therapeutic vulnerabilities." (PMID 41218118, 2025). "MiR-142-3p has a tumor suppressor role in CC, suppressing proliferation and invasion capacities by inhibiting frizzled class receptor 7 (FZD7)." (PMID 38201661, 2024). "The elevated protein expression level of FZD7 and restoration of FZD7 function effectively reverses the inhibitory effect exerted by the tumor suppressor miR-613 on RCC cell proliferation and invasion." (PMID 38886806, 2024). "In LC, lncRNA_DSCR8 promoted tumor cell progression by regulating the lncRNA_DSCR8/miR-485-5p/FZD7 axis 43, which was different from our ceRNA axie." (PMID 36605483, 2023). "IHC also showed that the staining intensity of FZD7 in the tumor tissue of BCL6-overexpressing nude mice was significantly weaker than that in the control group." (PMID 37060074, 2023). "The addition of Wnt inhibitors and rescue experiments further clarified that BCL6 inhibits the Wnt/β-catenin signaling pathway through direct transcriptional repression of the oncogene FZD7, thereby exerting its tumor suppressor effect in GC." (PMID 37060074, 2023). "Fzd7 modulates intestinal epithelial regeneration and immune homeostasis, and deletion of this gene increases the probability of inducing tumor growth." (PMID 36691900, 2023). "It is possible that a subpopulation of FZD7+ tumor cells is intrinsically more resistant to chemotherapy, or FZD7 is up-regulated in a subpopulation of cells that developed resistance." (PMID 37943878, 2023). "Recent studies have shown that in cervical and ovarian cancers, downregulation of FZD7 was accompanied by a decreased expression of vimentin and Snail and increased E-cadherin expression, and tumours presented an attenuated ability to invade and migrate." (PMID 35854234, 2022). "Fzd7 is a key receptor of the Wnt pathway, that is up-regulated in GC and CRC cells and associated with tumor invasion, metastasis, and cancer stem cell formation." (PMID 35655594, 2022). "Especially, a panel of WNT components, including WNT5A, WNT7B, GPC1, and FZD6 or FZD7, shows tumor tissue-specific increment in CSCC, HNSC, LUSC, and BTCC." (PMID 35850748, 2022). "The overexpression of Fzd7 has been shown in both GC and CRC cells and is associated with tumor invasion, lymphatic and organ metastasis, and poor patient survival." (PMID 35655594, 2022). "A recombinant soluble peptide fragment (rhFzd7) has been shown to antagonize Fzd7 by competitively binding with Wnt3a and exhibit anti-tumor and anti-angiogenesis activities in TNBC." (PMID 33585487, 2021). "The novel humanized antibody targeting Fzd7 (SHH002-hu1) exhibited extremely high affinity with Fzd7, and specifically targeted to Fzd7+ cells and tumor tissues." (PMID 33436039, 2021). "Compared to TNBC tumor tissues from control animals, which from Bevacizumab-treated mice displayed significantly more areas of intense hypoxia and more expression of Fzd7; furthermore, Fzd7 positivity was found specific to zones of low oxygen." (PMID 33436039, 2021).
tumor (continued). "This suggests an additional function of TG2 in CSC phenotype, spheroid proliferation, and tumour-initiating capacity modulated through the direct interaction with Wnt receptor Frizzled 7 (Fzd7)." (PMID 34205140, 2021). "Fzd7 knockdown delayed xenograft tumor formation, suppressed tumor growth, and impaired lung metastasis." (PMID 32894152, 2020). "Firstly, there is strong correlation of TCF7L1 with FZD7 expression, particularly in normal but also in tumor tissue." (PMID 32403323, 2020). "Another study also revealed that miR-144-3p suppressed tumor metastasis by targeting FZD7 (Frizzled-7) in GBM cells." (PMID 33046994, 2020). "Tumors derived from FZD7 shRNA-transfected cells grew much slower than those from control shRNA-transfected cells, indicating that Fzd7 knockdown inhibited tumor growth." (PMID 32894152, 2020). "FZD7 was expressed in tumor cells of 73 (73%; valid n = 100) primary GCs, 34 (54%; valid n = 63) lymph node metastases, 4 (50%; valid n = 8) distant metastases, and 10 (45.5%; valid n = 22) pretherapeutic biopsies." (PMID 31827644, 2019). "Tumor cells expressed FZD7 in the tumor center of 58 (58%; valid n = 100) and at the invasion front of 48 (48%; valid n = 100) primary GCs." (PMID 31827644, 2019). "The expression of FZD7 at the tumor surface, tumor center, and invasion front correlated significantly with each other (surface vs. center: p = 0.004; surface vs. invasion front: p < 0.001; center vs. invasion front: p < 0.001; data not shown)." (PMID 31827644, 2019). "FZD7 regulates tumor tumorigenesis by promoting cellular β-catenin accumulation and activation of Wnt signaling, including GBM." (PMID 31419987, 2019). "Here, we show that shRNA‐mediated stable knockdown of FZD7 not only reversed the Mes phenotype but also diminished anoikis resistance, cell survival, spheroids, and tumor formation." (PMID 30548372, 2019). "Subsequently, wound healing and Transwell invasion assays of the treated tumor cells showed that FZD7 overexpression partially reversed the inhibition of U87 and U373 cell migration and invasion caused by miR-504." (PMID 31419987, 2019). "One report has demonstrated that a monoclonal FZD7 antibody abrogated the stemness properties in FZD7-sensitive Wilm’s tumor cells." (PMID 29361730, 2018). "Wnt/β-catenin signaling is a key pathway for maintaining cancer stemness; this finding implies the use of FZD7 antibodies to target the population of tumor-initiating cells (T-ICs)." (PMID 29361730, 2018). "Subsequently, Tissue microarray (TMA)-IHC was performed to examine the protein expression levels of FZD7 in 252 primary ESCCs and their paired adjacent non-tumor tissues." (PMID 29029485, 2017). "Results revealed that FZD7 overexpression was significantly correlated with higher tumor stage (p = 0.001)." (PMID 27852064, 2016). "Accumulating evidence indicates that aberrant activation of the FZD7/Wnt pathway promotes carcinogenesis and tumor progression." (PMID 27409829, 2016). "Gene expression analyses showed that FZD7, the gene encoding a WNT receptor, was highly up-regulated in tumor samples from the highly metastatic derivatives relative to those from the parental line." (PMID 26808375, 2016). "FZD7 knockdown in MA-2 cells led to a significant reduction in tumor incidence, suggesting that FZD7 is essential for tumor initiation of MA-2 cells." (PMID 26808375, 2016). "In four microarray expression studies, the expression of FZD7 mRNA is significantly higher in GBM than that in the adjacent non-tumor tissues; The range ofFZD7 mRNA increase was 2.4- to 5.1- fold." (PMID 27852064, 2016). "The Fzd7 extracellular domain has also been shown to potently inhibit the growth of APC mutant CRC tumour cells in a mouse xenograft model." (PMID 27196929, 2016). "Firstly, the anti-Fzd7 monoclonal antibody targets a range of Frizzled receptors and has shown anti-tumor efficacy in a series of preclinical tumor models including pancreas, breast, and lung cancer." (PMID 27355964, 2016).
tumor (continued). "Recently, inhibition of FZD7 by the therapeutic monoclonal antibody OMP-18R5 was shown to decrease tumor growth and tumorigenicity of several human xenograft tumors." (PMID 27409829, 2016). "The Wnt receptor Frizzled-7 (FZD7) promotes tumor progression and can be currently targeted by monoclonal antibody therapy." (PMID 27409829, 2016). "Limiting dilution assays showed that the tumor initiating frequency of MA-2 cells was significantly higher than that of A375P cells, consistent with a link between FZD7-mediated tumor initiation and metastatic potential." (PMID 26808375, 2016). "A similar reduction in tumor initiation was observed in WM266-4 cells expressing FZD7 shRNA, although in this case the knockdown cells eventually grew into tumors in all the mice injected." (PMID 26808375, 2016). "More recently, one study reported that use of an anti-FZD antibody inhibited the binding of Wnts to FZD (such as FZD7) and inhibited the growth of human tumor xenografts." (PMID 24897117, 2014). "In one study a significant correlation between the expression of FZD7 and in vivo tumor formation was shown; indicating that FZD7 is essential for cancer cell development." (PMID 24897117, 2014). "Comparative analysis of gene expression in AC and SCC tumour tissues has additionally identified Wnt11 and its receptor Fzd-7 as potential regulators of SCC development." (PMID 23505429, 2013). "Furthermore, as previously demonstrated, these Fzd7 expressing cells mark not only tumor-initiating cells (TICs) but also mammary gland stem cells (MaSCs)." (PMID 41218118, 2025). "FZD7 is also highly expressed, particularly in the central regions of the tumor mass." (PMID 40943055, 2025). "Together with the in vivo transplantation studies, these experiments support our hypothesis that Fzd7-expressing cells harbor tumor initiating potential." (PMID 41218118, 2025). "Moreover, FZD7 has been highlighted for its involvement in tumor development predominantly in the gastrointestinal tract." (PMID 39198452, 2024). "FACS analysis confirmed that most of these tumor organoid cells were FZD7+ (approximately 81.7%)." (PMID 37943878, 2023). "The FZD7/Wnt axis may be blocked to drastically reduce the production of tumor-related proteins and to slow the HCC development." (PMID 37502362, 2023). "Previous reports indicate that Fzd7 participates in stem cell regeneration and tumor development." (PMID 36691900, 2023). "In addition, it has been reported that FZD7 can promote the tumor development of HCC cells in vivo via Wnt/β-catenin signal transduction in HBV-induced HCC." (PMID 36685852, 2022). "Re‐expression of either WT Fzd5 or Fzd7 can rescue the tumor growth but Fzd5 I199A or C538A." (PMID 35975457, 2022). "Consequently, SHH002-hu1 effectively targets Fzd7+ cells and Fzd7+ TNBC tumor tissues by specifically binding to Fzd7." (PMID 33436039, 2021). "miR-613 could inhibit cancer cell proliferation, migration, invasion and promotes apoptosis by targeting numerous oncogenes, including DCLK1, Fzd7, and SphK2.miR-613 had been stated to be down-regulated in different cancers and act as a tumor suppressor." (PMID 32592365, 2020). "Furthermore, Fzd7 was highly expressed in gastric tumours, and transmitted Wnt signalling to upregulate the transcription factor Myc, to promote tumour initiation and growth." (PMID 31288403, 2019). "Furthermore, we recently demonstrated that tumour initiation and growth in the gastric antrum requires Fzd7 dependant upregulation of Myc." (PMID 31288403, 2019). "Furthermore, we recently demonstrated that Wnt regulates Myc expression, via Fzd7, to control tumour initiation and growth in the stomach, regeneration in the intestine and homeostasis in the stomach." (PMID 31288403, 2019). "And FZD7 knockdown significantly reduced tumor sphere formation in patient derived xenograft tumor." (PMID 29789460, 2018).
tumor (continued). "In the animal model for tumor metastasis, introduction of exogenous FZD7 in ESCC cells could result in increased popliteal lymph nodes metastasis." (PMID 29029485, 2017). "To further examine whether inhibition of FZD7 expression could suppress the ESCC cell mobility and tumor metastasis in mouse model, we knocked down the endogenous FZD7 expression in KYSE30 and KYSE410 cells (KYSE30/KYSE410-sh1/3) by lentiviral transduction." (PMID 29029485, 2017). "Notably, FZD7 can be inhibited by the therapeutic monoclonal antibody Vantictumab (OMP-18R5) which showed potent anti-tumor effects in murine xenograft studies and is currently being tested in clinical trials for various solid cancers." (PMID 27409829, 2016). "Fzd7 also plays an important role during metastasis by regulating the critical stages in which epithelial cancer cells transition into mesenchymal cells when leaving the primary tumour (EMT), and then from mesenchymal to epithelial (MET) at the secondary site." (PMID 27196929, 2016). "Early studies have shown that blocking FZDs could inhibit angiogenesis and tumor growth, and application of the purified extracellular domain of FZD7 could decrease β-catenin/TCF4 transcriptional activity." (PMID 24897117, 2014). "In addition, the total RNA and protein of each representative tumor from the mice were used to analyze the expression levels of miR-199a and FZD7 by qRT-PCR and western blotting, respectively." (PMID 25313882, 2014). "Taken together, these results strongly suggested that miR-199a might function as a tumor suppressor partly by mediating the repression of FZD7 expression in HCC development." (PMID 25313882, 2014). "In GC, overexpression of Wnt ligands (Wnt2, Wnt3, and Wnt5A) and receptors (FZD7 and LRP5/6) is associated with more advanced disease, poorer prognosis, and elevated metastatic potential, while β-catenin and reduced APC expression further underline more aggressive tumor behavior." (PMID 40943055, 2025). "FZD7 expression is also elevated in a variety of stem cell populations, including human pluripotent stem cells and intestinal stem cells (25, –27), raising the possibility that cancer cells hijack functions of this receptor to establish tumor initiating potential." (PMID 41218118, 2025). "Therefore, BCL6 could directly repressed the transcription of FZD7 to inhibit the Wnt/β-catenin signaling pathway and acted as a tumor suppressor in GC." (PMID 37060074, 2023). "Hence, Fzd7 blockade may lead to the suppression of tumor cell growth by inhibiting the Wnt signaling pathway." (PMID 35655594, 2022). "Furthermore, soluble Fzd7 augmented the chemotherapeutic agents’ effect on inhibiting tumor growth." (PMID 35655594, 2022). "To further evaluate whether FZD7 is a prognostic marker for early or late ESCC, we studied the association of FZD7 overexpression with the survival rate in ESCC patients stratified by tumor staging." (PMID 29029485, 2017). "Research has shown that soluble FZD7 (sFZD7) and monoclonal antibodies targeting FZD7 can inhibit FZD receptor activity, resulting in tumour growth suppression." (PMID 41142820, 2025). "Specifically, the FZD1, FZD2, FZD6, FZD7, and FZD8 genes were found to be significantly overexpressed in tumor tissues compared to normal pancreatic tissues, based on mRNA expression data from TCGA and other public databases." (PMID 40943055, 2025). "Among the Wnt-related genes relevant to PCa, Wnt3a, Wnt5a, Fzd7, sFRP1, and ROR2 stand out due to their roles in modulating tumour behaviour under hypoxic conditions." (PMID 41007281, 2025). "FZD7, the most extensively studied Frizzled receptor in HCC, is upregulated in both tumor areas and surrounding dysplastic tissue." (PMID 40943055, 2025). "They identified AQP5, KiSS-1, FZD7, AURKB, UBE2C, and PTTG1 as overexpressed in recurrent CNs, suggesting these genes play a role in tumor progression." (PMID 39066950, 2024).
tumor (continued). "Among these 10 genes HDAC1, CASP3, REST, HMG20B, FZD7,GNAI3, FZD1 and EPHB4 had elevated expression in tumor group compared to the normal group, while KCNJ9 and SCRT1 were decreased." (PMID 38629068, 2024). "We compared the expression level of six frequently used markers for WNT activation (CTNNB1/beta-catenin, TCF1, TCF4, FZD7, MYC and CCND1) in normal and tumor tissue." (PMID 37149691, 2023). "Downregulation of FZD7 in TNBC cell lines MDA-MB-231 and BT-20 deactivated Wnt signaling resulted in decreased cell proliferation and tumor transformation." (PMID 36476410, 2022). "Consistent with the observed increase in WNT related genes in tumor cells, we saw high scores for WNT-related interactions (ligands Sfrp1 and Wnt5a and receptors Fzd6, Fzd7 and Lrp6) and significant BMP-related interactions (e.g. from Bmp4 with Bmpr1a)." (PMID 35600339, 2022). "For example, antibodies targeting the extracellular domain of FZD5, FZD7, and FZD10 have been successfully applied to inhibit the individual FZD-induced tumor growth in pancreatic ductal adenocarcinoma, Wilms’ tumor, and synovial sarcoma, respectively." (PMID 36620565, 2022). "This article analyzes publicly available gene and protein expression data and reveals the existence of a WNT5A/FZD2/FZD7/ROR2 signature, which correlates with tumor-infiltrating and mesenchymal cell marker expression." (PMID 33869179, 2021). "Our meta-analysis did not highlight any dramatic changes in gene expression for the FZD7 and DKK1 genes between normal and tumor tissue." (PMID 32403323, 2020). "In conclusion, we demonstrate that the FZD7‐TWIST1 axis is involved in the maintenance of Mes phenotype, resistance to anoikis and tumor formation through epigenetic modifications." (PMID 30548372, 2019). "To the contrary, we were unable to detect a significant correlation (after multiple testing) between tumor regression and the expression of MIST1 or FZD7, in both pretherapeutic biopsies and resected primary GCs." (PMID 31827644, 2019). "MiR-504 also functions as a tumour-suppressive miRNA that inhibits the proliferation and invasion of HCC cells by targeting Frizzled-7 (FZD7) and inhibiting Wnt/β-catenin signalling." (PMID 30953094, 2019). "We found increased expression of FZD6, FZD7, RYK, and PTK7 in tumors, as well as a highly significant increase in FZD7 in tumor-adjacent cells." (PMID 31261741, 2019). "Results showed that β-catenin/TCF activity is reduced in response to the disruption between FZD7 and DVL, leading to the suppression of tumor growth." (PMID 29361730, 2018). "FZD7 mRNA expression was significantly higher in the stage II, III or IV tumour tissues than in non-tumour tissues (P<0.005)." (PMID 19773752, 2009). "The expression levels of FZD7 mRNA in 135 primary CRC and 38 non-tumour tissues were examined by real-time PCR." (PMID 19773752, 2009). "Unlike conventional 2D cultures, MMTV-Wnt1 tumor-derived organoids preserve the complexity of the original tumors, including basal-luminal organization and basal-restricted Fzd7 expression." (PMID 41218118, 2025). "HOTAIR knockdown inhibited tumour growth in a xenograft mode, whereas killing of miR-129-5p reversed the silencing function of HOTAIR and FZD7 restored the suppressive function of miR-129-5p, suggesting that HOTAIR controls the miR-129-5p/FZD7 axis." (PMID 38528461, 2024). "However, from a prognostic perspective, CD5, SLCO1B1, and CD79A have been demonstrated to have protective value in various tumors, whereas ETV5, FZD7, SNX7, and SLC1A7 are involved in tumor progression." (PMID 37680641, 2023). "Using IHC score in individual LUSC tumor tissue as a reference, we found that the expression profiling of WNT7B, WNT5A, FZD7 and GPC1 could be divided into four sub-clusters." (PMID 35850748, 2022). "In addition, this carotenoid was reported to repress Wnt signaling via the down-expression of Wnt target genes, Fzd7, Nedd9 and Vim and the VEGF-α genes in 4T1 cells and mice tumor and lung tissues." (PMID 36079579, 2022).